PRELID3B (PRELI domain containing 3B)
Synonyms: C20orf45; SLMO2; dJ543J19.5; UPS2
Tractability: PROTAC: ubiquitination databases record sites on it.
Gene: Protein-coding gene on chromosome 20 (59,033,143 to 59,042,897, reverse strand). Ensembl gene ENSG00000101166.
Subcellular location (Human Protein Atlas): Nucleoplasm
Gene Ontology:
Molecular function: phosphatidylserine transfer activity; protein binding; phosphatidic acid transfer activity
Biological process: intermembrane phospholipid transfer; mitochondrial membrane organization; phospholipid transport
Cellular component: mitochondrial intermembrane space; mitochondrion
Genetic constraint (gnomAD): Loss-of-function variants: 9 observed, 15.13 expected, observed/expected ratio (o/e) 0.59, 90% interval 0.36 to 1.04. The upper end of that interval is the gene's LOEUF score, 1.04, which puts it in group 4 of 6, group 1 being the genes least tolerant of losing a copy. Missense variants: 156 observed, 208.46 expected, observed/expected ratio (o/e) 0.75, 90% interval 0.66 to 0.86. Synonymous variants: 56 observed, 69.63 expected, observed/expected ratio (o/e) 0.8, 90% interval 0.65 to 1.
Homologues: Orthologues: chimpanzee PRELID3B (99% identical), macaque PRELID3B (99% identical), dog PRELID3B (97% identical), guinea pig PRELID3B (96% identical), mouse Prelid3b (94% identical), rat Prelid3b (94% identical), tropical clawed frog prelid3b (86% identical), zebrafish prelid3b (81% identical), Drosophila melanogaster slmo (53% identical), Caenorhabditis elegans F15D3.6 (38% identical). Paralogues in human: PRELID3A (63% identical), PRELID1 (29% identical), PRELID2 (22% identical).
Diseases named in the same sentence as PRELID3B in open-access papers:
PRELID3B is named in the same sentence as 5 diseases in open-access papers, as found by Europe PMC text mining. Sharing a sentence is not in itself a finding about the gene and the disease.
PRELID3B shares sentences with these, for which no sentence is quoted: cancer (2 papers); breast carcinoma (1); influenza infection (1); lung carcinoma (1); tumor (1).